IL10 (interleukin 10)
Diseases named in the same sentence as IL10 in open-access papers (continued):
Sharing a sentence is not in itself a finding about the gene and the disease.
cancer (continued). "Furthermore, metastatic cancer has been associated with higher IL-10 levels than cancer without metastases." (PMID 22855687, 2012). "Therefore, it can bepostulated that Tregs can impair antitumor immune responses in cancer patients.In addition to naturally occurring CD4+CD25+ Tregs, also IL-10 producing Tr1cells have been demonstrated to contribute to ineffective antitumor immuneresponses in cancer patients." (PMID 18317534, 2007). "In the cancer patients who had detectable circulating preoperative C-reactive protein concentrations (n=41), log-transformed concentrations of C-reactive protein were significantly correlated with interleukin-6 (r2=0.62, P<0.001) and interleukin-10 (r2=0.33, P<0.001)." (PMID 17003778, 2006). "In the cancer patients who had detectable circulating postoperative C-reactive protein concentrations (n=35), log-transformed concentrations of C-reactive protein were significantly correlated with those of interleukin-6 (r2=0.66, P<0.001) and interleukin-10 (r2=0.33, P<0.001)." (PMID 17003778, 2006). "Cytokine profiling (e.g., IL‐10 and TNF‐α levels) is being explored as a means of monitoring the efficacy of FMT in patients with cancer." (PMID 41496455, 2026). "Induction of regulatory B cell (Breg) phenotypes, characterized by IL-10 (Interleukin-10), TGFβ (Transforming Growth Factorβ), PD-1 and PD-L1 (Programmed death ligand 1) expression, may be important components of immune responses in models of cancer and in patients." (PMID 40449958, 2025). "In particular, we examine the role of circRNAs in TGF‐β, IL‐6, IL‐10, TNF‐α, VEGF, FGF, PDGF, and chemokine signaling in cancer." (PMID 40356340, 2025). "TGF-β, TNF-α, IL-6, and IL-10 are a few pro-inflammatory cytokines that regulate TME in TNBC and promote cancer progression and invasiveness." (PMID 40933989, 2025). "Although little is known about how IL-10 impacts TNBC, there is mounting evidence that it plays a role in the growth of cancer." (PMID 40933989, 2025). "Among them, cancer inhibitory fractions CIF8 and CIF9 were able to induce the anti-inflammatory IL10 while suppressing the pro-inflammatory IFN-g in CD4+ T cells via Ca2+ channel modulation." (PMID 41155199, 2025). "This condition results in an expansion of splenic Treg and Th2 cell populations, elevated levels of IL-4 and IL-10, and an increase in local hypothermic Treg cells along with higher TGF-β1 concentrations in the cancer, thereby facilitating lung metastasis." (PMID 40881864, 2025). "This long-term immunosuppressive state is likely triggered by the stimulation of M2 macrophages by cancer cells, which release cytokines such as TGF-β, IL-6, and IL-10, all of which can weaken the immune response." (PMID 40636413, 2025). "Heterogeneity at post-intervention was moderate-to-high for CRP, IL-6, IL-6-CNS, IL-6-cancer, TNF-α, IL-10, IFN-γ, BDNF, and cortisol." (PMID 40281902, 2025). "First, regarding cytokines in AF, the prognostic impact of inflammatory cytokines in patients with malignant tumors has been investigated in a study that reported the presence of IL-1β, IL-6, IL-8, IL-12, TNF-α, and IL-10 in AF." (PMID 39755760, 2025). "ROS, IL-10 and TGFB1 produced by MDSCs negatively regulates CD8+ T cells activity against cancer cells." (PMID 39981232, 2025). "IL-24 is a member of the IL-10 cytokine family, signaling via the JAK/STAT3 signaling pathway to induce cancer cell apoptosis." (PMID 40175348, 2025). "These Bregs promote cancer cell growth by releasing TGF-β and IL-10, which suppress CD8+ T cell responses." (PMID 40136652, 2025). "In this secondary analysis of our randomized controlled CRBP-TS trial, we evaluated the effects of HOET on the cytokines IL-1ß, IL-2, IL-6, IL-10, IL-12p70, TNF-α, IFN-γ, and the mGPS of 145 cancer patients." (PMID 40498221, 2025).
cancer (continued). "The M2 macrophages secrete cytokines such as IL-10 and TGF-β, which promote angiogenesis and matrix remodeling, and create the favorable conditions for cancer cell proliferation, infiltration, and migration." (PMID 40109347, 2025). "Cancer cells achieve this by secreting immunosuppressive cytokines, such as transforming growth factor-beta (TGF-β) and interleukin-10 (IL-10), which inhibit the activity of effector immune cells." (PMID 40006583, 2025). "A meta-analysis examining serum inflammatory biomarkers following vitamin D supplementation in cancer patients revealed significant reductions in TNF-α, IL-6, and C-reactive protein (CRP) levels, while IL-10 levels remained unchanged." (PMID 39582404, 2025). "Once cancer is established, tumors create an immunosuppressive environment through the secretion of cytokines like TGF-β and IL-10, and the recruitment of Tregs." (PMID 40305493, 2025). "The Mφ-CM contained a number of EMT inducers, including CHI3L1, IL-10, IL-6, IL-8, and TNF-α, which are known to play a role in cancer metastasis, migration, invasion, chemotaxis, and endothelial cell junction retraction." (PMID 40678259, 2025). "Cytokines produced by Th2 cells, including IL-10, IL-4, and TGF-β, can promote the dissemination and metastasis of cancer cells in various cancers." (PMID 40356980, 2025). "These M2-like TAMs release anti-inflammatory cytokines, such as interleukin-10 (IL-10) and transforming growth factor-beta (TGF-β), which collectively contribute to the dampening of the immune response against cancer cells." (PMID 38175687, 2024). "Although small, these differences affected important signaling pathways (NGF-stimulated transcription, IL-10 signaling, PERK activity) and cancer genes (CBFA2T3, ETV4, FGFR1, GLI1, SGK1, and STAT3)." (PMID 38968069, 2024). "Intermittent hypoxia (IH) in OSA promotes cancer progression by upregulating HIF-1α and transforming growth factor β1 (TGF-β1), which alter cytokine levels, increase TNF-α and IL-10, and decrease IL-17, suppressing antitumor immunity." (PMID 39070143, 2024). "Several cytokines, including leptin, IL-1B, IL-6, IL-8, IL-23, IL-17, and IL-10, stimulate cancer progression, while others, including IL-2, IL-12, and IFN-γ, inhibit cancer proliferation and/or invasion." (PMID 37979099, 2024). "Further evaluation is warranted to elucidate the dose–effect relationship for the treatment suppression of IL10, TNF-α, and IL12p70 in monocytes, PMNs, and B cells under IgM stimulation as potential infections during the treatment for cancer patients." (PMID 39513832, 2024). "To explore similar mechanisms in other cancers, we conducted a correlation analysis of CD59 with macrophage, IL10, IL10RB, IL6, and IL6R on KIRC, CESC, GBM, HNSC, and STAD." (PMID 39518137, 2024). "Transforming growth factor-beta (TGF-β), IL-10, and vascular endothelial growth factor (VEGF) are some immunosuppressive cytokines that the cancer cells and the surrounding stromal cells secrete." (PMID 39594765, 2024). "The major signalling pathways specific to the cancer condition are VEGI, APRIL, IL10, and CD70, and these pathways mostly involve the signalling from immune cells." (PMID 39149248, 2024). "Monocytes secrete a variety of pro-inflammatory cytokines, such as interleukins IL-1, IL-6, IL-10, and TNF-α, which have been correlated with reduced survival and a worse prognosis in patients with malignant tumors." (PMID 39493767, 2024). "Activation of STAT3 in cancer cells leads to proliferation and suppression of apoptosis and we can observe that in BC where STAT3 is activated by elevated levels of IL-6 and IL-10." (PMID 38892394, 2024). "Loss of Lect2 fosters the accumulation/activation of M-MDSC, leading to the presence of M2-like TAMs and pro-tumorigenic cytokines (IL-4, IL-6, IL-10, and TGF-β) that can impair the activity of T cells in the fight against cancer." (PMID 38177412, 2024).
cancer (continued). "M2 macrophages produce high levels of anti-inflammatory cytokines, such as IL-10 and TGF-β, and in vitro promote cancer cell invasion." (PMID 39594814, 2024). "[K+]e elevation by necrotic cancer and cancer-infiltrating cells in the TME increased the expression and production of IL-10 and IL-8 in M2-MACs." (PMID 39273558, 2024). "We did not observe significant changes in circulating cytokine levels (IL-6, IL-8, IL-10, MCP-1 and IP-10) in patients with cancer undergoing systemic treatment after three months of nutritional support with whey protein-based oral supplements." (PMID 38892006, 2024). "Consistent with previous studies, we confirmed that macrophages co-cultured with cancer cells exhibited high expression of CD163, CD206, Arg1, and IL-10, markers indicative of an M2 phenotype." (PMID 39877420, 2024). "Our analysis indicated a positive correlation between B3GNT5 and immune activation markers, including CD276, PVR, NT5E, STING1, and TNF-SF18, as well as immunosuppressive genes TGF-ΒR1, IL-10PR, KDR, CD274, PDCD1LG2, IL-10, and IDO1 in the pan-cancer cohort." (PMID 39671359, 2024). "We did not observe significant changes in circulating cytokine levels (IL-6, IL-8, IL-10, MCP-1 and IP-10) in patients with cancer undergoing systemic treatment after three months of nutritional support with whey protein-based oral nutritional supplements." (PMID 38892006, 2024). "Pegilodecakin, a PEGylated form of IL-10, activated CD8+ T cell immunity in cancer patients by elevating IFN-γ and granzyme B levels." (PMID 39664443, 2024). "In malignant tumors, the polarized M2 macrophages produce and secrete cytokines such as CCL18, CCL20, CCL22, IL10, TGFB1, and GDF15." (PMID 39272860, 2024). "Both IL-10 and TGF-β have a pivotal role in the establishment of tolerance to allergens but can also be secreted by cancer cells." (PMID 38892863, 2024). "Prior studies have demonstrated the significance of RBM47 in the post-transcriptional regulation of IL-10, thereby enhancing the regulatory capabilities of B cells and implicating RBM47 in cancer immunity modulation." (PMID 38914961, 2024). "We investigated correlations of immunosuppressive markers (e.g., PD-L1, CTLA-4, and IL-10) in CD4+ and CD8+ T cells from cancer mucosa of GC patients." (PMID 37153541, 2023). "In this study, we tested the cancer cell uptake ability of the NL formulation and investigated the potential of the M13–NL formulation to prevent CAC in the azoxymethane (AOM)-exposed IL10−/− mouse model." (PMID 37765299, 2023). "Therefore, targeting IL-10 may provide a new therapeutic opportunity for cancer." (PMID 36835413, 2023). "Peripheral blood mononuclear cells supernatant also showed increased levels of IL-6, IL-8, IL-10, IL-18, macrophage inflammatory protein 1 gamma (MIP-1γ) (cancer-promoting) and TNF-α (cancer-suppressive)." (PMID 37681925, 2023). "They produce IL-10 and TGF-β that suppress the activity of NK cells, T and B lymphocytes in the TME, allowing the proliferation and survival of cancer cells." (PMID 37340387, 2023). "The researchers demonstrated, in mouse models and in healthy volunteers and cancer patients, that APAP is able to induce up-regulation of regulatory T cells (Treg) and signaling of their soluble stimulatory mediator, interleukin (IL)-10." (PMID 37754504, 2023). "Among these factors is IL-10 which can impede the function of CD4+ and CD8+ T cells and promote immunosuppressive cells like Treg3; hence, promoting cancer development and progression." (PMID 37501757, 2023). "Our own studies confirm the influence of cytokines (i.e., concentrations of IL-1A, IL-1B, IL-2, IL-6, IL-10, TNF, and IL-4) on the emergence of fatigue in all its dimensions in patients with cancers of the reproductive organs at various stages of treatment." (PMID 36834426, 2023).
cancer (continued). "Functions of certain cytokines are explored; CCA and cancer stromal cells secrete inflammatory cytokines, such as IL-1, IL-6, IL-8, IL-10, TNF-α, and TGF-β, to promote cancer growth, metastasis, and immune evasion." (PMID 36883059, 2023). "We found that MDSC secreted cytokines IL-6, IL-10, IL-1β are the dominant factors elevating MDR expression in cancer cells, neutralization of MDSC secreted IL-6, IL-10, IL-1β reversed the MDR trait." (PMID 38304256, 2023). "M2 macrophages secrete anti-inflammatory cytokines such as IL-10, CCL18, and CCL22, which are beneficial to cancer cell growth." (PMID 37758759, 2023). "Interestingly, higher IL-10, which has anti-inflammatory properties, was previously found to be associated with less sedentary time and greater physical activity in a healthy sample without cancer." (PMID 37568698, 2023). "Tregs release suppressive cytokines such as interleukin-10 (IL-10) and TGF-β that inhibit CD8+ T cell function and enhance cancer cell escape from the immune attack." (PMID 38263981, 2023). "This CM contains cytokines, including interleukin-10, TGF-β, Hep growth factor, and vascular endothelial growth factor, which induce cell proliferation, migration, and invasion of the cancer cells." (PMID 36112670, 2023). "Collectively this observation suggests that MDSC augments early generation of drug resistance of cancer cells by IL-6/STAT1 and IL-10/STAT3 axis." (PMID 38304256, 2023). "NKs are the first line of defense against infectious agents and cancer cells by secreting multiple chemokines (CCL3, CCL4, CCL5, and XCL1), cytokines (IFN-γ, TGF-β, and IL-10) and growth factors (GM-CSF)." (PMID 37928272, 2023). "IL-10 can also inhibits CD4+ T cell proliferation and suppresses activation of immune effector cells such as T cells to assist cancer cell escape from immune surveillance." (PMID 37612278, 2023). "CF33-hNIS-antiPDL1 treatment produced functional anti-PD-L1 scFv, which blocked surface PD-L1 binding of live cancer cells and increased CD8+CD107α+ and CD4+CD107α+ T cell percentages while decreasing EGF, PDGF, soluble anti-PD-L1, and IL-10." (PMID 37762490, 2023). "Few articles investigated the predictive value of inflammatory biomarkers [interleukin (IL)-1β, IL-6, IL-10, TNF-α, and MMP-2 and -9] in the peritoneal fluid of cancer patients who underwent surgery and experienced AL in different locations." (PMID 37601530, 2023). "Of the shared measures in both sexes, IL-6 and IL-10 increased the most as the disease progressed (DFSO) or worsened (clinical score) and in patients with BMI > 30 and those with prior cancer treatment." (PMID 37998327, 2023). "Here, it was observed that the expression of IL-6, IL-10, IL-1β and VEGF were found to be significantly upregulated in supernatant from MDSC in comparison to cancer cell supernatant." (PMID 38304256, 2023). "In this review, inflammatory processes in cancer are discussed, focusing on cytokines IL-6, IL-10, and TNF-α, which play an important role in the inflammatory response, preventing or increasing different disorders, including cancer." (PMID 36771154, 2023). "The result is relevant, given that the overexpression of IL-10 and TGF-β in cancer are key cytokines in the generation of an immunotolerant status, which affects the proliferation of T cells and avoids the maintenance of antitumor function." (PMID 36661506, 2022). "Both LPS- and IL-10-stimulated macrophages induce the phosphorylation of EGFR, Akt, and ERK1/2 in cancer cells." (PMID 35955576, 2022). "The interactions between immune cells, cancer cells, necrotic cells, and adipocytes result in interesting dynamics and lead to the secretion of important cytokines such as HMGB1, IL12, IL10, and IL6." (PMID 35294447, 2022). "Based on the integral role of each gene in different cancers, we took the opportunity to focus on novel potential regulatory crosstalk among the INPP5A, HLA-G1, IL-10, and MMP-21 in ESCC." (PMID 36437782, 2022).
cancer (continued). "On the other hand, immunosuppressive responses including M2 macrophage infiltration and IL-10 secretion were alleviated, demonstrating that the hydrogel-based continuous release of DOX and R837 can provide an effective cancer treatment strategy." (PMID 36145656, 2022). "The main features of these cells are the generation of high levels of IL-10, TGF-β, and VEGF and low levels of IL-12, TNF-α, and IL-1β that help generate vascular production and cancer metastasis." (PMID 36362044, 2022). "Tregs can also suppress NK cell function through TGFβ surface presentation and promote T cell exhaustion via IL-10 and PRDM1 in mouse models of cancer." (PMID 35414042, 2022). "The results revealed that CD45 was positively correlated with the expression levels of genes characteristic of exhausted T cells across cancers, such as CXCL9, IL10, CD28, IDO1 and CCR4." (PMID 36061172, 2022). "From the outcome of the present study, it was found that physical exercise can reduce cancer incidence by improving immunity markers such as TNF-α, IL-6, IL-10, and NK cells." (PMID 35935260, 2022). "A number of cytokines and growth factors, such as TGF-β, IL-10, IFN-γ and EGF function as regulators of MICA expression in different types of cancer cells." (PMID 35967396, 2022). "Free light chains (FLCs), regulatory cytokines such as IL‐10, TGFβ, lipocalin‐2 (LCN‐2) and chemokines (e.g., CCCL1), promote cancer progression; however, CCCL5 chemokine has demonstrated an anticancer role." (PMID 35344301, 2022). "The M2-type cytokines (IL-10) and cancer-promoting cytokines (VEGF-A) produced by M2-polarized macrophages further promoted cancer progression and angiogenesis." (PMID 35326397, 2022). "A systematic review of 34 studies showed that IL-6 and TNF were associated with the severity of oral mucosal tissue damage in patients with cancer; the most investigated cytokines were IL-6, TNF, and IL-10." (PMID 35476641, 2022). "Secretion of anti-inflammatory cytokines like IL‐10, TGFβ-1, and CTLA4 promotes the suppressive phenotype of Treg which is immensely exploited by cancer cells." (PMID 35517798, 2022). "Both cancer cells and PSC-derived CAFs secrete IL-18, IL-10, and TGF-β, all of which diminish NK-cell function." (PMID 36077755, 2022). "FN1, IL10, and MYC activation were related to the poor prognosis, indicating a pivotal role in cancer progression." (PMID 36389789, 2022). "The results showed that IL-6, IL-10, and TNF concentrations in the saliva of patients with cancer were significantly higher in the post-index group than in the pre-index group and significantly positively correlated with OM grade." (PMID 35476641, 2022). "On the other hand, IL-10 and TGF-β are immune modulating cytokines that contribute to immunosuppressive TME and promote cancer progression and metastasis." (PMID 36551547, 2022). "The increase of TNF, IL-1β, and IL-10 secretion in healthy colonocytes (V BM alone and with hPA120 treatments; p < 0.05) and for TNF and IL-10 in cancer cells (treatments except O BM + hPA120 and V BM, respectively; p > 0.05) were stated." (PMID 36296918, 2022). "Suppression of IL-10 improves checkpoint blockade and reduces T cell exhaustion in mouse models of CLL, but counterintuitively, pegylated IL-10 can also have potent immune stimulatory effects on CD8 T cells and is being explored as an anti-cancer therapy." (PMID 35414042, 2022). "RIgE antibodies and CCCL5 chemokine have an anticancer role, whereas IgG4, free light chains, Il‐10, TGF‐β, lipocalin‐2, CCL1 chemokine promote cancer progression." (PMID 35344301, 2022). "Tregs, MDSC, and TAMs are known to secrete interleukin 10 (IL-10), transforming growth-factor β (TGF-β), vascular endothelial growth factor, and prostaglandins, leading to immune evasion, neo-angiogenesis, cancer cell proliferation, migration, and survival." (PMID 35740542, 2022).